LINC01187 (long independently transcribed non-coding RNA 1187)
Synonyms: KIDR
Gene: Long non-coding RNA gene on chromosome 5 (170,191,579 to 170,199,141, reverse strand). Ensembl gene ENSG00000249601.
Diseases named in the same sentence as LINC01187 in open-access papers:
LINC01187 is named in the same sentence as 11 diseases in open-access papers, as found by Europe PMC text mining. Sharing a sentence is not in itself a finding about the gene and the disease. The quoted sentences say what the papers report.
breast carcinoma (1 paper, 2019). "In the presented study, we constructed and validated a 10‐lncRNA‐based signature (HAGLR, MIR210HG, RGMB‐AS1, TMEM161B‐AS1, CADM3‐AS1, LINC00293, LINC00910, LINC01187, PDZRN3‐AS1 and ZBED5‐AS1) to predict RFS for patients with breast cancer." (PMID 31429520, 2019).
chromophobe renal cell carcinoma (1 paper, 2023). Chromophobe renal cell carcinoma is a rare subtype of renal cell carcinoma, originating from the intercalating cells of the collecting ducts and macroscopically manifesting as a well-circumscribed, highly lobulated, solid tumor that is usually diagnosed at an early stage. "Interestingly, both FOXI1 and LINC01187 genes were recently reported to be involved in chromophobe renal cell carcinoma." (PMID 37056054, 2023).
glomerulonephritis (1 paper, 2023). A renal disorder characterized by damage in the glomeruli. "Interestingly, we documented that LINC01187 is significantly down‐regulated in human renal pathologies, including DN and RPGN, as well as additional murine models of renal pathologies, including NTS‐induced glomerulonephritis and I/R." (PMID 37056054, 2023).
kidney diseases (1 paper, 2023). "LINC01187 down‐regulation in renal diseases, such as DN and RPGN, suggests a potential involvement of this RNA in disease pathophysiology." (PMID 37056054, 2023). "Together, these observations imply a negative association of LINC01187 with kidney diseases through a potential anti‐apoptotic action." (PMID 37056054, 2023).
tumor (1 paper, 2024). "We also evaluated the spatial distribution of the two HOT cellular populations within individual HOT tumor by examining the distribution of the L1CAM and LINC01187 expression in a single HOT tissue section through dual RNA-ISH staining." (PMID 37994665, 2024).
LINC01187 also shares sentences with these, for which no sentence is quoted: diabetic nephropathy (1 paper); hepatocellular carcinoma (1); lung carcinoma (1); renal oncocytoma (1); renal tumors (1); thyroid papillary cancer (1).